MLC1 (modulator of VRAC current 1)
Description:
Transmembrane protein mainly expressed in brain astrocytes that may play a role in transport across the blood-brain and brain-cerebrospinal fluid barriers. Regulates the response of astrocytes to hypo-osmosis by promoting calcium influx. May function as regulatory protein of membrane protein complexes such as ion channels (Probable).
Synonyms: KIAA0027; MLC; LVM; VL
Tractability: Antibody: UniProt places it where antibodies can reach, with high confidence; its Gene Ontology location is reachable by antibodies, with high confidence; UniProt predicts a signal peptide or a membrane-spanning region. PROTAC: ubiquitination databases record sites on it; its protein half-life has been measured.
Gene: Protein-coding gene on chromosome 22 (50,059,391 to 50,085,969, reverse strand). Ensembl gene ENSG00000100427.
Subcellular location: Membrane; Cell membrane; Cytoplasm, perinuclear region; Endoplasmic reticulum
Subcellular location (Human Protein Atlas): Cytosol
Gene Ontology:
Molecular function: identical protein binding; protein binding; protein-containing complex binding
Biological process: positive regulation of intracellular transport; regulation of response to osmotic stress; caveolin-mediated endocytosis; cellular response to cholesterol; vesicle-mediated transport; protein transport
Cellular component: basolateral plasma membrane; cell-cell junction; cytoplasm; cytoplasmic vesicle; cytosol; endoplasmic reticulum; endosome; membrane; perinuclear region of cytoplasm; plasma membrane; caveola; clathrin-coated vesicle; early endosome; lysosome; membrane raft; recycling endosome; apical plasma membrane; astrocyte end-foot
Genetic constraint (gnomAD): Loss-of-function variants: 32 observed, 41.42 expected, observed/expected ratio (o/e) 0.77, 90% interval 0.58 to 1.04. The upper end of that interval is the gene's LOEUF score, 1.04, which puts it in group 4 of 6, group 1 being the genes least tolerant of losing a copy. Missense variants: 459 observed, 485.92 expected, observed/expected ratio (o/e) 0.94, 90% interval 0.87 to 1.02. Synonymous variants: 190 observed, 209.52 expected, observed/expected ratio (o/e) 0.91, 90% interval 0.81 to 1.02.
Gene-disease validity (ClinGen):
ClinGen rates the evidence that MLC1 causes each of these diseases.
megalencephalic leukoencephalopathy with subcortical cysts 1 (autosomal recessive): Definitive.
Homologues: Orthologues: mouse Mlc1 (89% identical), rat Mlc1 (89% identical), guinea pig MLC1 (86% identical), rabbit MLC1 (84% identical), pig MLC1 (81% identical), macaque MLC1 (80% identical), dog MLC1 (79% identical), chimpanzee MLC1 (73% identical), tropical clawed frog mlc1 (57% identical), zebrafish mlc1 (53% identical).
Diseases named in the same sentence as MLC1 in open-access papers:
MLC1 is named in the same sentence as 45 diseases in open-access papers, as found by Europe PMC text mining. Sharing a sentence is not in itself a finding about the gene and the disease. The quoted sentences say what the papers report.
megalencephalic leukoencephalopathy (36 papers, 2010 to 2025). "Mutations of PV-AEF molecules, such as MLC1 and GlialCAM, cause a human developmental disease, called megalencephalic leukoencephalopathy with subcortical cyst, in which gliovascular functions are dysregulated." (PMID 37829206, 2023). "Megalencephalic leukoencephalopathy with subcortical cysts (MLC) is a neurodevelopmental disorder caused by biallelic mutations in the MLC1 gene in two-third of cases (MLC1)." (PMID 35096710, 2021). "Megalencephalic leukoencephalopathy with subcortical cysts (MLC) is a rare early-onset leukodystrophy caused by genetic mutations in the genes encoding glial membrane proteins MLC1 and GlialCAM." (PMID 34847774, 2021). "MLC1 is a membrane protein mainly expressed in astrocytes, and genetic mutations lead to the development of a leukodystrophy, megalencephalic leukoencephalopathy with subcortical cysts disease." (PMID 34847774, 2021). "In the present work, we analyzed for the first time the relationships between the gap-junction protein Cx43 and MLC1, the astrocytic protein whose mutations are responsible for megalencephalic leukoencephalopathy with subcortical cysts (MLC)." (PMID 32521795, 2020). "Variants in the MLC1 gene have been implicated in megalencephalic leukoencephalopathy with subcortical cysts, an autosomal recessive disorder characterized by macrocephaly, progressive motor and cognitive features, and variable presence of subcortical cysts." (PMID 32209057, 2020). "Whole exome sequencing had revealed a founder mutation in MLC1 gene in individuals from Nalband community suffering from megalencephalic leukoencephalopathy with subcortical cysts (MLC)." (PMID 31554517, 2019). "Of the many success stories of GUaRDIAN, the diagnosis of a rare mutation in megalencephalic leukoencephalopathy with subcortical cysts 1 (MLC1) gene in leukodystrophy was instrumental in community service in the form of affordable diagnostics." (PMID 31554517, 2019). "Megalencephalic leukoencephalopathy with subcortical cysts is a neurodegenerative disease caused by mutations in MLC1 or GlialCAM." (PMID 27322623, 2016). "Mutations in HEPACAM give rise to the neurodegenerative disease megalencephalic leukoencephalopathy with subcortical cysts (MLC) since mutated hepaCAM prevents shuttling of MLC1 protein to astrocytic junctions in the plasma membrane." (PMID 27819278, 2016). "Interesting advances in the comprehension of these mechanisms emerged from the study of genetic diseases distinguished by chronic brain edema and caused by mutations in specific astrocytic proteins, such as MLC1 in the megalencephalic leukoencephalopathy with subcortical cysts (MLC) disease." (PMID 36078064, 2022). "Among these is MLC1, a protein highly expressed in perivascular astrocytes and whose mutations cause megalencephalic leukoencephalopathy with subcortical cysts (MLC), an incurable leukodystrophy characterized by macrocephaly, chronic brain edema, cysts, myelin vacuolation, and astrocyte swelling." (PMID 36078064, 2022). "Another slowly progressive autosomal recessive neurological disorder affecting white matter and causing progressive gait, fine motor, and cognitive disturbance, megalencephalic leukoencephalopathy with subcortical cysts due to biallelic MLC1 mutations, can also be unmasked by 22q13.33 deletions." (PMID 31879555, 2019). "The modulator of VRAC current 1 (MLC1) is associated with Megalencephalic Leukoencephalopathy with subcortical cysts and it could be related to melanoma survival and chemoresistance through mitogen-activated protein kinases (MAPK) - extracellular signal-regulated kinases (ERK) pathway." (PMID 34777208, 2021). "Work on MLC1 knock-out mice furthermore suggested that MLC1, a membrane protein of unknown function associated to megalencephalic leukoencephalopathy, might stabilize GlialCAM in the plasma membrane and thus act as an additional binding partner within the ClC-2/GlialCAM complex." (PMID 25339907, 2014).
megalencephalic leukoencephalopathy (continued). "The discovery of the MLC1 protein originated from the identification of patients affected by the same LD, megalencephalic leukoencephalopathy with subcortical cysts (MLC disease), who carried mutations in the same gene, subsequently named MLC1." (PMID 41465860, 2025). "For instance, VRAC has been implicated in the modulation of cell volume changes in astrocytes observed in megalencephalic leukoencephalopathy with cysts (MLC), which is associated with mutations in MLC1 or GlialCAM." (PMID 37538172, 2023). "3D MRF was performed on normal C57BL/6 mice with different ages, megalencephalic leukoencephalopathy with subcortical cyst 1 wild type (MLC1 WT, control) mice, and MLC 1 knock-out (MLC1 KO, leukodystrophy) mice using a 3 T MRI." (PMID 38102606, 2023). "Megalencephalic leukoencephalopathy with subcortical cysts (MLC) is a rare type of vacuolating leukodystrophy (white matter disorder), which is mainly caused by defects in MLC1 or glial cell adhesion molecule (GlialCAM) proteins." (PMID 35628339, 2022). "Megalencephalic leukoencephalopathy with subcortical cysts (MLC), the white matter disease of the brain, is caused by the expression defect of the MLC1 or GlialCAM gene products, predominantly confined to the plasma membrane." (PMID 34531445, 2021). "Megalencephalic leukoencephalopathy with subcortical cysts (MLC, MIM# 604004) is an autosomal recessive inherited disease mostly resulting from MLC1 mutations." (PMID 22416245, 2012). "We also observed only three overlapping genes between differentially expressed genes in these three selected modules: FGFBP2, GFOD1, MLC1, which were functionally enriched for revascularization, glycometabolism, Megalencephalic leukoencephalopathy with subcortical cysts pathways." (PMID 30683112, 2019). "We can speculate that this pattern of expression may explain, in part, the childhood developmental regression typical of megalencephalic leukoencephalopathy (MLC), a disorder caused by variants in MLC1." (PMID 30875393, 2019).
megalencephalic leukoencephalopathy with subcortical cysts (17 papers, 2012 to 2026). "Loss of function of the astrocyte protein MLC1 causes Megalencephalic Leukoencephalopathy with subcortical Cysts (MLC), a leukodystrophy characterized by white matter edema and slow neurological deterioration." (PMID 41331492, 2026). "Megalencephalic leukoencephalopathy with subcortical cyst (MLC) is a rare leukodystrophy primarily caused by mutations in two genes: MLC1, encoding a membrane protein of unknown function, and GlialCAM, a cell adhesion molecule." (PMID 41314544, 2025). "Mutations in the gene MLC1 are found in approximately 80% of patients with the inherited childhood white matter disorder megalencephalic leukoencephalopathy with subcortical cysts (MLC), which is a leukodystrophy that is caused by mutations in MLC1 or GLIALCAM." (PMID 24378849, 2013). "In the mouse nervous system, HEPACAM (Hepatic And Glial Cell Adhesion Molecule, also known as GlialCAM) and MLC1 (Megalencephalic Leukoencephalopathy With Subcortical Cysts 1) stabilize CLCN2 in the plasma membrane by reducing its turnover rate and improving CLCN2 gating." (PMID 40140900, 2025). "Also high expression of MLC1 (megalencephalic leukoencephalopathy with subcortical cysts 1), a gene with so far unknown gene function, was detected in CD56+ cells." (PMID 25984272, 2014).
leukodystrophy (13 papers, 2013 to 2026). Leukodystrophies are a group of rare, progressive, metabolic, genetic diseases that affect the brain, spinal cord and often the peripheral nerves. "Diffuse WM loss in the rTg-DI corpus callosum is pronounced, and with MLC1 already implicated in leukodystrophy, it is possible that MLC1 upregulation is of mechanistic importance in the astrocytic response as a CAA-ri specific DAA." (PMID 38600214, 2024). "Loss-of-function mutations not only in CLCN2 but also in GLIALCAM and MLC1, with which ClC-2 may form ternary complexes in glia, can cause leukodystrophy in humans and mice." (PMID 33187987, 2021). "In our study, MLC1 KO (leukodystrophy model) mice showed lower MWF values compared to MLC1 WT (control model) mice." (PMID 38102606, 2023). "We also show that additional disruption of mlc1 in glialcama knockout zebrafish or in Glialcam knockout mice does not potentiate the vacuolating phenotype characteristic of MLC disease, indicating that loss-of-function mutations in these genes cause leukodystrophy through a common pathway." (PMID 31752924, 2019). "As both MWF and PLP results assessed from the corpus callosum demonstrated a significant reduction by MLC1 deletion, this may suggest that MWF is more sensitive to show changes due to leukodystrophy, however, a larger number of samples with different ages would be needed to confirm this assumption." (PMID 38102606, 2023).
astrocytoma (4 papers, 2020 to 2022). "To investigate the possible role of Cx43 in MLC pathogenesis, we studied Cx43 properties in astrocytoma cells overexpressing wild type (WT) MLC1 or MLC1 carrying pathological mutations." (PMID 32521795, 2020). "With the aim of shedding light on MLC molecular pathogenesis, we here investigated Cx43 properties in U251 astrocytoma cell lines overexpressing MLC1 WT or carrying pathological mutations." (PMID 32521795, 2020). "To study the relationship between MLC1 and CaMKII, we used the already characterized U251 human astrocytoma cell lines stably overexpressing the human recombinant MLC1 wild-type (MLC1-WT)." (PMID 36078064, 2022). "Both WB and IF analysis of Cx43 distribution in MLC1-expressing astrocytoma lines indicated that WT MLC1 expression favored the partitioning of Cx43 in the Triton-insoluble gap-junction fraction." (PMID 32521795, 2020). "Interestingly, in different cellular models (human astrocytoma cells and MLC1 KO primary astrocytes) MLC1-inhibits specific intracellular signaling cascades responsible for astrocyte activation and proliferation following brain inflammation/stress (pEGFR/pERK/pNF-kB/PLCγ/pSTAT3)." (PMID 35008700, 2021). "CHX experiments confirmed this speculation, demonstrating that MLC1 expression in U251 astrocytoma cells is able to increase stability of Cx43 proteins at the plasma membrane, as indicated by its slower degradation time in WT when compared to MLC1 mutant-expressing cells." (PMID 32521795, 2020). "Since in U251 cells we recently revealed MLC1-mediated inhibition of phospho-ERK1/2 (pERK1/2) that, in U251 cells, is constitutively activated, we hypothesized that MLC1 might indirectly alter Cx43 trafficking by inhibiting pERK1/2 activation in astrocytoma cells." (PMID 32521795, 2020). "By using newly generated U251 astrocytoma cell lines expressing WT or mutant MLC1, we found that WT but not mutated MLC1 expression favors Cx43 partitioning in the Triton-insoluble membrane protein compartment that corresponds to connexin-assembled gap-junctional plaques." (PMID 32521795, 2020). "We here investigated possible structural and functional relations between MLC1 and Cx43 by using an already characterized MLC cellular model represented by U251 astrocytoma cells overexpressing MLC1 wild type (WT) or carrying pathological mutations." (PMID 32521795, 2020). "This notion is further supported by the fact that in astrocytoma/glioblastoma cells, where MLC1 is virtually absent (or minimally expressed), changes in intracellular Ca2+ do not affect ICl,swell." (PMID 36078064, 2022).
Leukoencephalopathy (4 papers, 2010 to 2021). This term describes abnormality of the white matter of the cerebrum resulting from damage to the myelin sheaths of nerve cells. "Since GLIALCAM mutations entail a vacuolating human leukoencephalopathy, we previously generated Glialcam−/− mice to study its interaction with ClC-2 and with MLC1, another binding partner of GlialCAM that also underlies human leukoencephalopathy." (PMID 33187987, 2021). "The Mlc1 gene encodes megalencephalic leukoencephalopathy with subcortical cysts-1 (Mlc1), a membrane protein expressed specifically in GFAP-positive cells in the adult brain." (PMID 29238610, 2017). "Downregulated genes included amyloid beta precursor protein‐binding, family a member 2 (APBA2); glycoprotein m6a (GPM6A); megalencephalic leukoencephalopathy with subcortical cysts 1 (MLC1); ankyrin repeat and btb domain containing 2 (ABTB2); and ring finger protein 43 (RNF43)." (PMID 19793339, 2010).
ischemia (3 papers, 2013 to 2024). A hypoperfusion of the BLOOD through an organ or tissue caused by a PATHOLOGIC CONSTRICTION or obstruction of its BLOOD VESSELS, or an absence of BLOOD CIRCULATION. "Activated MMP-2 degrades susceptible sarcomeric and cytoskeletal proteins including troponin I (TnI), myosin light chain-1 (MLC-1), and α-actin, leading to the acute contractile dysfunction observed in ischemia/reperfusion injury." (PMID 25559243, 2015). "Intracoronary administration of the Doxy, ML-7, and L-NAME mixture during ischemia led to a decrease in MMP-2 (p = 0.0134), MMP-9 (p = 0.017), MLC1 (p = 0.003), and BNP-26 (p = 0.002) concentrations in the blood as compared to the MI." (PMID 38672140, 2024). "This increased level of the truncated form of MLC1 was negatively correlated with recovery and positively correlated with increased MMP-2 activity, which was correlated with the duration of ischemia." (PMID 24455428, 2013). "In our most recent work using isolated cardiomyocytes subjected to 60 minutes of simulated ischemia, ONOO−-modified MLC1 increased degradation of MLC1 by MMP-2, and ONOO− scavengers protected cardiomyocytes from contractile dysfunction triggered by oxidative stress." (PMID 24455428, 2013). "For the reason that the observed posttranslational modifications in MLC1 from myocytes subjected to simulated ischemia are similar, but not identical to those observed in MLC1 isolated from I/R hearts, use of the chemically induced H-R model is a better choice than the simulated ischemia model." (PMID 24455428, 2013).
brain edema (2 papers, 2022 to 2026). Increased intracellular or extracellular fluid in brain tissue. "Our results provide a basis for future investigations into how MLC1 is involved in tuning the mechanical properties of intact astrocytes, how this relates to astrocyte volume regulation and brain fluid dynamics, and how disruption of these processes leads to chronic brain edema in MLC." (PMID 41331492, 2026).
epilepsy (2 papers, 2021). A brain disorder characterized by episodes of abnormally increased neuronal discharge resulting in transient episodes of sensory or motor neurological dysfunction, or psychic dysfunction. "The low level of perivascular Kir4.1 observed in Mlc1 KO mice might link MLC to epilepsy." (PMID 34723793, 2021).
Macrocephaly (2 papers, 2010 to 2016). Occipitofrontal (head) circumference greater than 97th centile compared to appropriate, age matched, sex-matched normal standards. "We note that among the annotated genes were for example TUBA1 and MLC1, both directly correlated with brain abnormalities in humans suffering of lissencephaly and macrocephaly, respectively." (PMID 20444278, 2010).
schizophrenia (2 papers, 2005 to 2022). A major psychotic disorder characterized by abnormalities in the perception or expression of reality. "Of 1,183 genes that mapped to nominally significant DMPs, some were previously associated with BD or schizophrenia, including MLC1, ESR1, KCKN5, L1CAM, CPEB1 and GABBR2." (PMID 35922419, 2022). "Thus, mutations in MLC1 are causative for MLC, but can be excluded as a susceptibility factor in schizophrenia." (PMID 16225677, 2005).
Alzheimer disease (1 paper, 2022). A progressive, neurodegenerative disease characterized by loss of function and death of nerve cells in several areas of the brain leading to loss of cognitive function such as memory and language. "Interestingly, a recent study investigated the expression of MLC1 across diseases with a strong neuroinflammatory component: Alzheimer’s disease (AD), MS, and Creutzfeldt-Jacob disease." (PMID 35227276, 2022).
dementia (1 paper, 2018). Loss of intellectual abilities interfering with an individual's social and occupational functions. "Like DTNA, hippocampal MLC1 expression robustly predicts dementia status while TCX expression is strongly associated with P-tau levels." (PMID 30120299, 2018). "Evaluation of this microarray data revealed strikingly consistent associations with the Allen Aging, Dementia, and TBI dataset for each of the four genes (AQP4, DTNA, MLC1, FXYD1)." (PMID 30120299, 2018). "MLC1 and FXYD1 were chosen from the larger pool of novel gene candidates based on the associations identified with dementia status and tau pathology." (PMID 30120299, 2018).
gastric cancer (1 paper, 2021). A primary or metastatic malignant neoplasm involving the stomach. "Bupivacaine decreased the phosphorylation of MYPT1 and MLC1, which reduced the migration of gastric cancer cells." (PMID 34950031, 2021).